IGF1 (insulin like growth factor 1)
Diseases named in the same sentence as IGF1 in open-access papers (continued):
Sharing a sentence is not in itself a finding about the gene and the disease.
Hyperinsulinemia (continued). "Hyperinsulinemia in AN patients may increase the binding of insulin and IGF-R and may also reduce IGF-binding proteins (IGFBPs), thus increasing biologically active IGF-1; this results in the development of hyperkeratosis and papillomatosis." (PMID 34438601, 2021). "A reduction in concentrations of IGFBP-1 in hyperinsulinemia condition might stem from higher bioavailability of the free IGF-1, as well as the decreased levels of total IGF-1 and IGFBP-3." (PMID 31601230, 2019). "Hyperinsulinemia may increase the bioavailability of IGF-1 and IGF-2 by inhibiting the synthesis of IGF-binding protein 1 and 2 and by intensifying IGF-1 hepatic production." (PMID 29184536, 2017). "Given that the mean birth weight of our cohort is in the normal range, the lower IGF-1 levels appear to be independent of the birth weight and possibly a specific effect of hyperinsulinism." (PMID 24228030, 2013). "Hyperinsulinemia increases serum free testosterone levels by reducing the production of hepatic sex hormone-binding globulin (SHBG), stimulates androgen production triggered by LH and insulin-like growth factor 1 (IGF-1), and enhances IGF-1 bioactivity by suppressing IGF-binding protein production." (PMID 40362363, 2025). "Postprandial hyperinsulinemia results in the suppression of Insulin-Like Growth Factor Binding Protein-1 (IGFBP-1), thereby increasing free IGF-1.Under conditions of caloric restriction, mammals produce less IGF-1, and its synthesis in the liver becomes refractory to GH stimulation." (PMID 39578883, 2024). "By peripherally inhibiting hepatic synthesis, hyperinsulinemia decreases serum sex hormone binding globulin (SHBG), favoring free circulating androgens, and decreasing insulin-like growth factor binding protein-1 (IGFBP-1), allowing more IGF-1 to be accessible locally and peripherally." (PMID 37791160, 2023). "Hyperinsulinemia induces a decrease in insulin-like growth factor binding protein-1 and 2 (IGFBP-1 and 2) and reduces sex hormone binding globulin (SHBG) levels, resulting in an increase in free estrogen and androgen and insulin-like growth factor-1 (IGF-1) levels." (PMID 36755926, 2023). "However, in patients with hyperinsulinemia not only is more insulin secreted, but the production of IGFBP-1 and IGFBP-2 is diminished, therefore permitting a higher concentration of active IGF-1 which can stimulate insulin receptors (IR) on endometrial tumor cells." (PMID 35439978, 2022). "Furthermore, hyperinsulinemia stimulates an increase of IGF-1 level through hepatic activation of growth hormone receptor (GHR), resulting in increased secretion of growth hormone (GH) which stimulates IGF-1." (PMID 33920079, 2021). "In addition, hyperinsulinemia decreases expression of insulin-like growth factor binding proteins 1 and 2 (IGFBP1 and IGFBP2) and thereby activates insulin-like growth factor-1 (IGF-1), which could also lead to the onset of neoplastic cells." (PMID 33807522, 2021). "Hyperinsulinemia may also promote carcinogenesis indirectly through its effects on IGF-1, as insulin inhibits IGF-1 binding proteins and thus increases the bioavailability of IGF-1." (PMID 26690494, 2015). "However, hyperinsulinemia and hyperglycemia can also lead to increased hepatic IGF-1 production independent of growth hormone." (PMID 23050968, 2012). "Elevated prolactin levels may also normalize IGF-1 levels in GHD patients without hyperinsulinism." (PMID 38152125, 2023). "In patients without hyperinsulinemia, IGF binding proteins (IGFBP-1 and IGFBP-2) control the amount of active IGF-1 that can act on cells to induce cell proliferation." (PMID 35439978, 2022).
prostate carcinoma (455 papers, 1997 to 2026). A carcinoma that arises from epithelial cells of the prostate gland. "On the one hand, epidemiological studies to date clearly indicate the relationship between higher levels of circulating IGF-1 and an increased risk of prostate cancer development (especially low-grade cancer)." (PMID 39941741, 2025). "Epidemiological studies have consistently demonstrated that elevated IGF-1 levels are associated with an increased risk of several cancers, including breast, colorectal, and prostate cancers." (PMID 40428567, 2025). "Insulin-like growth factor-1 (IGF-1) is associated with prostate cancer (PCa) development and lethality and exhibits immunosuppressive properties in other models." (PMID 41184420, 2025). "In conclusion, the result of this study has shown a significant positive association of serum insulin and insulin-like growth factor-1 levels with prostate cancer Gleason score and grade." (PMID 39781138, 2024). "Our research also observed positive association of insulin and insulin-like growth factor-1 levels with Gleason score and grade of prostate cancer." (PMID 39781138, 2024). "Some studies have shown that elevated glycosylated hemoglobin (HbA1c) is negatively associated with the risk of developing prostate cancer, due to lower concentrations of insulin-like growth factor-1 (IGF-1) in men with higher glycosylated hemoglobin (HbA1c)." (PMID 39076779, 2024). "We assessed the association of free IGF-1 with prostate cancer risk overall and by time to diagnosis, and also with risk by tumor subtypes according to histological grade, tumor stage, and aggressiveness." (PMID 38831273, 2024). "Recent epidemiological studies tried to establish association of insulin-like growth factor-1 and insulin with prostate cancer incident and mortality; however, the reported literature is inconsistent." (PMID 39781138, 2024). "Prospective study demonstrated that insulin-like growth factor-1 (IGF-1) is positively associated with the risk of developing prostate cancer." (PMID 39076779, 2024). "This study aimed to analyze the serum levels of lipids, insulin, insulin-like growth factor-1 (IGF-1) and testosterone and to identify their association with the risk of benign prostatic hyperplasia, prostate cancer and its grading." (PMID 39781138, 2024). "In long-term DM, insulin-like growth factor 1 receptor (IGF-1R) is reduced, and elevated IGF-1 levels correlate with increased prostate cancer risk." (PMID 38034011, 2023). "In prostate cancer, glioblastoma, and neuroblastoma, cancer metastasis is reduced by PDZ1i, which is caused by inhibition of insulin-like growth factor-1 (IGF-1), FAK, and integrin signaling, respectively." (PMID 37298370, 2023). "Increased bioavailability of IGF-1, increased binding of IGF-1 and IGF receptors, and increased intensity of IGF-1 action predispose to the induction of prostate cancer." (PMID 38260162, 2023). "Previous studies have shown that increased IGF-1 levels were associated with increased risk of prostate cancer." (PMID 36525222, 2023). "A clinical trial has demonstrated a close association between circulating IGF-1 and prostate cancer development and progression." (PMID 35053528, 2022). "Higher levels of insulin like growth factor-1 (IGF-1) have been found to be associated with a higher risk of developing prostate cancer." (PMID 36172282, 2022). "IGF-1 is also implicated in castration-resistant PCa and has been shown to activate androgen receptor (AR) signaling in prostate cancer cells via the IGF-1R-forkhead box protein O1 (FOXO1) signaling axis." (PMID 35370981, 2022). "In extensive prospective studies and meta-analyses, elevated IGF1 levels have been implicated in developing colorectal, premenopausal breast, and prostate cancer." (PMID 36295107, 2022).
prostate carcinoma (continued). "As a result, IGF-1 was not only linked to an increased risk of prostate cancer, but it was also playing a role in carcinogenesis by promoting cell proliferation and interfering with the process of cell death." (PMID 35903701, 2022). "Bufadienolide, a traditional Chinese drug Chan’Su-derived cardiac glycoside, caused G1 arrest of breast and prostate cancer cells by inhibiting insulin-like growth factor-I (IGF1)-activated phosphorylation of mTOR, S6K1, and 4EBP1." (PMID 36139919, 2022). "Of note, the expression of IGF-1 variants has been associated with prostate cancer development, including in human PIN tissues." (PMID 35457063, 2022). "The level of insulin-like growth factor 1 (IGF-1) in the human body is associated with prostate cancer due to the mitogenic and antiapoptotic effects on prostate epithelial cells." (PMID 35205105, 2022). "Insulin-like growth factor-1 (IGF-1) is a growth hormone and is implicated in prostate cancer progression." (PMID 35053528, 2022). "Insulin-like growth factor-1 (IGF-1)-related signaling is associated with prostate cancer progression." (PMID 35053528, 2022). "There are conflicting reports as to the influence of serum IGF-1 levels and the risk of developing prostate cancer." (PMID 33816477, 2021). "In the European Prospective Investigation into Cancer and Nutrition (EPIC) study, circulating IGF1 concentration was positively associated with a significant increase in the risk of prostate cancer." (PMID 33920379, 2021). "Epidemiological studies have suggested that elevated circulating serum insulin-like growth factor-1 (IGF-1) levels are associated with the development of advanced prostate cancer." (PMID 34682865, 2021). "Preclinical studies indicate that weight loss suppresses the growth of prostate cancer by reducing blood levels of IGF-1 and reducing inflammation accompanying obesity." (PMID 33546190, 2021). "Lycopene acts as an inhibitor of IGF-1, which is an identified risk factor for prostate cancer, promoting the processes of proliferation and differentiation of cancer cells." (PMID 33546190, 2021). "Insulin‐like growth factor‐1 (IGF‐1) was suggested to be positively associated with the risk of prostate cancer in meta‐analyses." (PMID 34606688, 2021). "The circulating level of IGF1 coupled with IGFBPs has been correlated with the risk of developing various cancers, including breast, lung, colon, and prostate cancers through human epidemiological studies." (PMID 34178997, 2021). "Elevated serum IGF1 levels are associated with increased risk, particularly in thyroid, colorectal, breast and prostate cancer." (PMID 34440844, 2021). "On the contrary, genes whose loss/down-regulation was implicated in prostate cancer cell invasion, metastasis formation and worse prognosis (AR, IGF1, IGF2, TGFB3, SEMA3E) were down-regulated in NE-like versus AdenoPCa tumors." (PMID 32041153, 2020). "Serum IGF-1 levels within the higher quintile of normality have been associated with a higher risk of prostate cancer, 18 times higher in men older than 60 years of age." (PMID 33292786, 2020). "Our findings thus provide the underlying molecular mechanisms of IGF-1-induced prostate cancer proliferation, progression, and metastasis controlled by post-translational modifications of Flot-1." (PMID 30631151, 2019). "The association between metabolic syndrome and prostate cancer focused on the function of insulin, IGF-1, and their receptors as strategic factors in downstream signaling pathways that stimulate tumor growth." (PMID 29794984, 2018). "Overall, epidemiological and experimental evidence to date suggest a positive association between circulating IGF‐1 and prostate cancer risk." (PMID 27734632, 2016). "High levels of IGF-1 have also been shown to be positively associated with colorectal, lung, and prostate cancers." (PMID 27598322, 2016). "Associations between prostate cancer and IGF‐1 have been studied extensively, and consistently show a positive association." (PMID 27734632, 2016).
prostate carcinoma (continued). "Epidemiological studies have reported a positive association between circulating IGF‐1 levels and various primary cancers, such as breast, colorectal, and prostate cancer." (PMID 27734632, 2016). "Components of MetS are linked to an increased risk of prostate cancer and MetS-related biomarkers such as insulin, insulin-like growth factor-1 (IGF-1), leptin and adiponectin are implicated in the involvement of tumorigenesis." (PMID 27349496, 2016). "Prospective studies have shown that people with circulating IGF-1 have an increased risk of common epithelial cancers such as breast, colon and prostate cancer." (PMID 26541196, 2015). "Fat intake is also negatively correlated with insulin-like growth factor binding protein-3 (IGFBP-3), the major binding protein of IGF-1 in plasma, which is also independently associated with the risk of prostate cancer." (PMID 25533015, 2014). "In this retrospective study, we aimed to evaluate the association of four polymorphisms in three LD blocks of the IGF-1 on the survival of prostate cancer patients with bone metastasis at initial diagnosis." (PMID 23530598, 2013). "IGF-IR activation has mitogenic and antiapoptotic effects in prostate tumor cells and circulating serum levels of IGF1 have been associated with increased risk of prostate cancer." (PMID 23152004, 2013). "Insulin-like growth factor-I (IGF-1) is considered as a factor contributing to prostate cancer risk." (PMID 23823800, 2013). "Epidemiologic studies have reported an association between elevated IGF-1 levels and increased prostate cancer risk." (PMID 23823800, 2013). "IGF-1 is known to regulate e.g. cell proliferation and apoptosis and high levels of circulating IGF-1 have been associated with increased prostate cancer risk." (PMID 23861774, 2013). "Polymorphisms of the IGF-1, especially C-T haplotype in the LD block 3 were associated with worse survival of prostate cancer patients with bone metastasis at initial diagnosis." (PMID 23530598, 2013). "Recent meta-analysis revealed that men with higher circulating IGF-1 levels had an increased risk of prostate cancer compared with men with lower IGF-1 levels and the levels of circulating IGF-1 had a heritable component." (PMID 23530598, 2013). "Elevated serum levels of leptin, insulin and IGF-1 are all associated with high risk of prostate cancer incidence and progression and long-term exercise is known to reduce serum levels of these and other endogenous hormones." (PMID 23861774, 2013). "Similar findings were reported for prostate cancer risk with a 2.4-fold higher risk for men in the highest quartile of IGF-1 concentration compared to men in the lowest." (PMID 23983688, 2013). "Recent evidence indicates increased risk of prostate cancer in individuals with high serum IGF1 levels, whereas risk was decreased in those with high levels of IGFBP-3." (PMID 22792137, 2012). "It is unlikely that FFM causes prostate cancer, but instead provides a marker of testosterone or IGF1 activities involved with retaining lean mass as men age." (PMID 22257467, 2012). "Leptin and insulin/IGF-1 are high in obese men and suppress androgen levels, moreover leptin has been implicated in advanced and high-grade prostate cancer in two case–control studies." (PMID 21266978, 2011). "IGF-1 has been implicated in the initiation and progression of several different cancers including prostate cancer." (PMID 20537156, 2010). "Elevated levels of blood IGF-1 have been associated with an increased risk of advanced stage prostate cancer." (PMID 19171036, 2009). "For example, PSA cleaves insulin-like growth factor binding proteins resulting in local release of IGF-1, which has been positively associated with prostate cancer risk." (PMID 18827812, 2008). "While serum levels of IGF decrease with age, within the aged population those individuals with the highest levels of serum IGF-1 have the greatest risk of developing epithelial cancers such as prostate cancer." (PMID 18182993, 2008).
prostate carcinoma (continued). "The risk of developing prostate cancer for men in the top quartile of IGF-1 compared with the bottom quartile was 1.31 (95%CI: 1.03–1.67)." (PMID 16804529, 2006). "Insulin-like growth factor (IGF)-1 is associated with a higher risk of prostate cancer." (PMID 39941741, 2025). "For instance, studies have shown that dairy protein, especially from milk, increases circulating IGF-1 levels, which may partly explain its association with prostate cancer risk." (PMID 40428567, 2025). "Moreover, the intake of dairy products is associated with increased IGF-1 levels, promoting proliferation of prostate cancer cells, and an increased secretion of pro-inflammatory cytokines, such as IL-6, IL-1β and tumor necrosis factor (TNF) alpha." (PMID 39954205, 2025). "IGFBP-1 binds with IGF-1, which increased the risk of prostate cancer and cardiometabolic diseases." (PMID 38575325, 2024). "For example, dairy and especially milk intake has been related to moderately higher risk of prostate cancer, and it has been hypothesised that the underlying mechanism is through dairy protein intake increasing circulating IGF-1." (PMID 38643440, 2024). "Furthermore, men with prostate cancer who received endocrine treatment and underwent surveillance were at greater risk of developing IGF-1-related cancers." (PMID 37341814, 2023). "A multiethnic cohort study demonstrated that IGF1 also played a role in prostate development and carcinogenesis, while the inherited variation of IGF1 may affect the risk of prostate cancer." (PMID 37705744, 2023). "Increased insulin-like growth factor 1 was associated with increased risk of prostate cancer." (PMID 37965470, 2023). "Comparable to our results, a statistically significant association using only one cis-SNP as an instrumental variable, but statistically non-significant associations when using both the cis- and multiple trans-SNPs was observed in a MR study on IGF-1 and prostate cancer risk." (PMID 37833736, 2023). "Milk and dairy products are associated with increased blood levels of insulin-like growth factor 1, which may promote the development of prostate cancer." (PMID 37513568, 2023). "It has been suggested that an increased circulating concentration of IGF-1 might be associated with an increased calcium intake and prostate cancer risk." (PMID 36612074, 2022). "Raised BP may downregulate IGF‐binding protein‐1 (IGFBP‐1), and this might increase the risk of prostate cancer by increasing IGF‐1 activity." (PMID 34939344, 2022). "We hypothesize that the regulation of IGF-1 signaling contributing to prostate cancer risk in a real-world setting is increased by intestinal factors." (PMID 35370981, 2022). "More recently, the largest systematic review of studies on the association of IGF-1 with the risk of prostate cancer concluded that there is a 21% increased risk of prostate cancer per SD increase in IGF-1, with a stronger association with more aggressive and advanced cases." (PMID 33557137, 2021). "A justifiable mechanism is that vitamin D supplementation increases IGF-1 concentration, which is consistent with the hypothesis that IGF-1 may increase the risk of prostate cancer." (PMID 33546190, 2021). "Childhood or adolescent milk consumption may influence the risk of prostate cancer later in life through elevated IGF-1 levels in the critical period of prostate development during puberty." (PMID 33546190, 2021). "However, we found a suggestive positive association of genetically predicted IGF‐1 levels with prostate cancer in UK Biobank (OR 1.10; P = .04) and a similar non‐significant estimate in the Biobank Japanese Project (OR 1.08; P = .24)." (PMID 32717139, 2020). "Insulin-like growth factor-1 (IGF-1) is associated with the risk of prostate cancer." (PMID 29757237, 2018). "We hypothesized that low IGF‐1 levels might be associated with high‐grade disease, because IGF‐1 induces prostate cancer development via the androgen axis or has similar effects to testosterone." (PMID 29992746, 2018).